TBX21 (T-box transcription factor 21)
Diseases named in the same sentence as TBX21 in open-access papers (continued):
Sharing a sentence is not in itself a finding about the gene and the disease.
autoimmune disease (10 papers, 2017 to 2025). A disorder resulting from loss of function or tissue destruction of an organ or multiple organs, arising from humoral or cellular immune responses of the individual to their own tissue constituents. "Notably, AtM B cells were also featured with the high expression of ZEB2, TBX21, and SREBF2, consistent with specific TFs of age-associated B cells (ABCs) in autoimmune diseases." (PMID 41459486, 2025). "TBX21 together with TGIF1 are predicted to target TAGAP, that is a known regulator of T cell differentiation and autoimmune diseases." (PMID 39090334, 2024). "Age-associated B cells (ABCs) are T-box transcription factor 21 (TBX21, also called T-bet)+CD11c+CD11b+CD21− memory B cells that arise with age and are expanded in patients with autoimmune diseases such as SLE." (PMID 38256093, 2024). "In autoimmune disorders, the expansion of ABCs and CD14+ Atypical B cells is significantly higher; therefore, conditional targeting of the transcription factor T-bet encoded by TBX21, which is important and sufficient for ABCs formation, could be an efficient and novel therapeutic target." (PMID 36544777, 2022).
malaria (10 papers, 2014 to 2023). Malaria is a serious and sometimes fatal disease caused by a parasite that commonly infects a certain type of mosquito which feeds on humans. "In the malaria model, c-Maf-depletion led to greater acute-phase pathology, associated with enhanced expression of Tbx21 and production of IFN-γ." (PMID 32117317, 2020). "Of note, we detected a subset of memory B cells expressing ITGAX (CD11c) and TBX21 (T-bet) that resemble ABCs previously reported to be expanded in ageing, following malaria vaccination and in systemic lupus erythematosus (SLE) patients." (PMID 35549406, 2022). "However, no direct binding of c-Maf to the Tbx21 locus was observed in the malaria model, indicating that c-Maf could regulate the expression of Tbx21 through indirect mechanisms." (PMID 32117317, 2020).
viral infection (10 papers, 2017 to 2024). "Other reports have shown associations between TBX21 with the immune response to viral infection or eradication or hepatocarcinogenesis." (PMID 38781172, 2024). "In B cells, TBX21 elicits a Th1 cell immune response, induces the secretion of antibodies IgG1 and IgG3, and induces memory B cells that elevate the expression of the immune response upon viral infection." (PMID 38510965, 2024). "Furthermore, the expression of T-box transcription factor 21 (Tbx21/T-bet), known as a master regulator of type 1 immunity commonly mounted against viral infection, was also found to be overexpressed in NK cells and peaking at 5 dpi." (PMID 37350967, 2023). "Indeed, GC Tfh cells induced following viral infections, where Th1 inflammatory responses predominate, express Bcl-6, Tbx21, IFN-γ, and IL-21, consistent with the induction of Th1-type Tfh cells." (PMID 31827000, 2020). "Hence, persistent viral infection can be excluded as a cause for functional and phenotypical differences between CTLs from P14 Tbx21+/+, P14 Tbx21-/- and P14 Tbx21E/E mice." (PMID 32991634, 2020).
Autoimmunity (9 papers, 2020 to 2024). The occurrence of an immune reaction against the organism's own cells or tissues. "A unique subset of B cells that express high levels of CD11c, an integrin, and T-bet (Tbx21), a transcription factor, is generated in humans during autoimmunity and chronic infection." (PMID 33815408, 2021). "Notably, they express Tbx21, linking them to autoimmunity in a similar manner to that observed in lupus-like autoimmunity in mice." (PMID 39599617, 2024). "As revealed by evidencing studies, NLRC3 increases many genes related to the activation of Th1/Th17/T cells, such as Ifng, Tnf, Il17f, Il17a, and Tbx21; also, study reveals that Nlrc3 expression in T cells inhibits autoimmunity as well as CD4+ T cell responses specific for virus." (PMID 38436712, 2024). "Moreover, the necessity and importance of elucidating the role of transcription factor T-bet (TBX21) in the pathogenesis of human autoimmunity are addressed." (PMID 33163863, 2020). "FOXO1 represses TBX21-mediated effector functions to promote memory CD8+ T cell formation and Treg function; thus, a loss of FOXO1 may drive continued T cell effector function in the skin during melanocyte autoimmunity." (PMID 33384688, 2020).
systemic lupus erythematosus (8 papers, 2016 to 2023). An autoimmune multi-organ disease typically associated with vasculopathy and autoantibody production. "Notably, these cells also expressed Tbx21 (T-bet), a signature transcription factor of autoreactive B cells associated with a Th1 response and lupus-like autoimmunity." (PMID 37907556, 2023). "Nineteen probes for 16 lupus-relevant genes (Abca1, Apobec3, Ccr7, Ceacam3, Ets1, Foxp3, Hdac1, Ifng, Irf9, Itgam, Jhdm1d, Mmp9, Oscar, Slc4a1, Tbx21, and Tlr7) were identified from the database of male murine spleen." (PMID 30246031, 2018). "Recent studies have shown that genetic variants in TBX21 and IFNG are connected with risk of systemic lupus erythematosus (SLE)." (PMID 26916970, 2016).
melanoma (6 papers, 2018 to 2024). A malignant, usually aggressive tumor composed of atypical, neoplastic melanocytes. "Transcription factor enrichment analysis indicated that TBX21 was the most important TF in C4 Melanoma CORO1A and was also associated with M1 modules." (PMID 37435067, 2023). "TBX21 is the most important TF in C4 Melanoma CORO1A and is associated with M1 modules." (PMID 37435067, 2023). "In vitro experiments further showed that TBX21 knockdown dramatically decreases melanoma cells’ proliferation, invasion, and migration." (PMID 37435067, 2023). "In order to further investigate the function of TBX21 in melanoma, we performed in vitro experiments." (PMID 37435067, 2023). "In order to further investigate the function of TBX21 in melanoma, we performed in vitro tests to further investigate the function of TBX21 in melanoma cells." (PMID 37435067, 2023). "The results of multivariate COX regression analysis revealed TBX21 as an independent protective factor for patients with melanoma." (PMID 37435067, 2023). "All phenotypic and functional markers of T cells—CD3E, CD4, CD8B, FOXP3, GZMB, PRF1 and TBX21—were expressed at higher levels in melanoma patients with high ETV7 expression." (PMID 33424867, 2020). "More recently, transcriptomic comparison of CD4+ T cells at baseline and antigen specific CD4+ T cells after neoantigen vaccination in melanoma patients revealed significant induction of effector and memory T cell gene expression programs including Tbx21." (PMID 29423108, 2018). "In addition, the expression of ZNF93 and TBX21 in C4 melanoma CORO1A most significantly differed between other melanoma subtypes." (PMID 37435067, 2023). "Besides, the key TFs of melanoma cell subtypes were identified, including TBX21, the core TF of M1 modules, and C4 Melanoma CORO1A." (PMID 37435067, 2023). "Furthermore, the cell function experiment was used to confirm the function of TBX21 in both A375 and WM-115 melanoma cell lines." (PMID 37435067, 2023). "LASSO regression analysis was used to filter TFs further in order to identify a biomarker that could predict the prognosis of patients with melanoma, based on which seven TFs (TBX21, MYB, GFI1, NFE2L3, TFAP2C, HEY2, NR2F2) were selected." (PMID 37435067, 2023). "Furthermore, patients with high expression of TBX21, the most highly regulated transcription factor (TF) of C4 melanoma CORO1A, had higher survival prospects." (PMID 37435067, 2023). "Therefore, a slower colony formation rate was seen in TBX21 knockdown cells, suggesting that TBX21 may be essential for the proliferation of the melanoma cell line." (PMID 37435067, 2023). "Thus, we inferred that TBX21 might impact the response of melanoma cells to NK and T cells by regulating the activation of genes associated with NK and T cells." (PMID 37435067, 2023). "Furthermore, to identify the independent protective or risk TFs of overall survival for patients with melanoma, we applied multivariate COX regression analysis and found that TBX21 is an independent protective factor with HR (0.55, 95%CI: 0.45-0.69) for patients with melanoma." (PMID 37435067, 2023). "The heatmap was used to demonstrate the expression levels of the genes TBX21, ZNF799, HEY2, ZNF580, IRF4, CREB3, and ZNF93 during the pseudotime trajectories of four distinct subtypes of melanoma cells." (PMID 37435067, 2023).
multiple sclerosis (6 papers, 2018 to 2025). A progressive autoimmune disorder affecting the central nervous system resulting in demyelination. "The protective role of TBX21-1514T>C polymorphism in susceptibility to multiple sclerosis." (PMID 30886677, 2018). "For example, Tbx21-expressing Th1 cells can induce microglial activation and neuroinflammation in neurodegenerative diseases such as Alzheimer’s disease and multiple sclerosis." (PMID 40162097, 2025). "Parnell GP and colleagues investigated the gene expression level of two distinct transcription factors encoded by TBX21 and EOMES genes in T- and NK cells in patients with multiple sclerosis (MS)." (PMID 37950255, 2023).
Sepsis (6 papers, 2017 to 2025). Sepsis is defined as life-threatening organ dysfunction caused by a dysregulated host response to infection. "Likewise, a decrease of TBX21, evident in sepsis TD CD8+ T cells, can cause impaired cytotoxicity." (PMID 41208955, 2025). "While sepsis NK cells maintained TBX21 activity, EOMES activity was significantly downregulated in sepsis." (PMID 41208955, 2025). "The decrease in JUN and TBX21 in the sepsis population of TD CD8+ T cells may contribute to impaired cytotoxic capability through the development of a dysfunctional state." (PMID 41208955, 2025). "TBX21, GNLY, PRF1, and IL2RB represent the immune status in sepsis." (PMID 41139765, 2025). "Likewise, when focusing on TFs related to the regulation of cytotoxicity genes (TBX21, EOMES, JUN, and RUNX3), alterations are evident within the sepsis cells." (PMID 41208955, 2025). "In contrast, the Tbx21 and Eomes genes were not inhibited by the methylation process, which facilitated the induction of the Th1 immune response and its maintenance during sepsis." (PMID 28439500, 2017).
colorectal cancer (5 papers, 2022 to 2025). A primary or metastatic malignant neoplasm that affects the colon or rectum. "TBX21, a member of the T-box transcription factor family, is involved in modulating the biological behavior of several malignancies such as lung and colorectal cancers, and has been shown to be closely linked with tumor immune regulation." (PMID 41343099, 2025). "For instance, in colorectal cancer, TBX21 inhibits the proliferation of tumor cells and promotes their apoptosis by regulating the ARHGAP29/RSK/GSK3β signaling pathway." (PMID 41573646, 2025). "Our results suggest that TBX21 may function as a tumor suppressor in colorectal cancer, with its overexpression inhibiting CRC cell migration and EMT." (PMID 39744435, 2025). "However, the role of TBX21 in colorectal cancer (CRC) metastasis remains unclear." (PMID 39744435, 2025). "In microsatellite stable colorectal cancer, butyrate produced by Fusobacterium inhibits histone deacetylase in CD8+ T-cells, inducing the expression of the TBX21 gene, which suppresses PD-1 expression, alleviates T-cell exhaustion, and thus enhances the efficacy of immunotherapy." (PMID 40177243, 2025).
diabetes (5 papers, 2017 to 2025). "For example, T-bet-deficient, non-diabetic mice are protected from diabetes 11, and TBX21 is overexpressed in the peripheral blood leukocytes of patients with late-onset Alzheimer's disease." (PMID 39744435, 2025). "Treatment of BDC mice with αCD3 Ab (clone 2C11), a therapy shown to reverse diabetes in NOD mice, however, decreased expression of Foxo1-axis genes but increased expression of TCR-driven genes (Irf4, Nr4a1, Cd25, Cd69, Tbx21) in PLN BDC CD4+ T cells." (PMID 34314385, 2021).
lung carcinoma (5 papers, 2018 to 2025). "For example, in lung cancer, TBX21 affects the progression of the tumor and the prognosis of patients by promoting the self-renewal and survival ability of lung cancer stem cells through the activation of the IL-4 signaling pathway." (PMID 41573646, 2025). "Functional studies indicated that downregulating TBX21 in lung cancer cells decreased the fraction of cancer stem cells and their sphere and tumor initiation frequency." (PMID 29615105, 2018).
lymphoma (5 papers, 2021 to 2025). A malignant (clonal) proliferation of B- lymphocytes or T- lymphocytes which involves the lymph nodes, bone marrow and/or extranodal sites. "On the other hand, other TFH lymphomas share some characteristics, such as the cell of origin, a more common TBX21 subtype, and genetic variation such as RAS family mutation and epigenetic regulators, with AITL." (PMID 33990228, 2021). "In other TFH lymphomas (N = 11), the TBX21 subtype (N = 10/11, 90.9%) was more common than the GATA3 subtype (N = 1/11, 9.1%)." (PMID 33990228, 2021). "AITL and other TFH lymphomas showed the TBX21 subtype more commonly than the GATA3 subtype." (PMID 33990228, 2021). "Comparing the staining results, the TBX21 subtype is more common in AITL and other TFH lymphomas than the GATA3 subtype." (PMID 33990228, 2021). "Interestingly, the upregulated transcriptome of these lymphomas also includes the transcriptional factor TBX21 (also known as T‐BET), the cotranscriptional regulator EOMES, and TBX21‐dependent gene signatures." (PMID 35895495, 2022).
Obesity (5 papers, 2021 to 2024). Accumulation of substantial excess body fat. "Fas cell surface death receptor (Fas), versican (Vcan), T-box transcription factor 21 (Tbx21), angiotensin I converting enzyme (Ace), and serpin family E member 2 (Serpine2), metabolic markers associated with obesity, were increased in the obese group." (PMID 38728395, 2024). "The T-bet gene (Tbx21) is highly conserved between mice and humans, as are its target genes and many pathways in obesity and metabolism." (PMID 39664730, 2024). "The higher transcription of mRNA FOXP3 and IL-10 (Treg markers), accompanied by a high transcription of TBX21 and IFNG (Th1 markers), GATA3 and IL-4 (Th2 markers) indicated the inflammatory status in the group with obesity and an altered Treg function." (PMID 37215211, 2023).
sarcoidosis (5 papers, 2013 to 2025). Sarcoidosis is a multisystemic disorder of unknown cause characterized by the formation of immune granulomas in involved organs. "TBX21, a Th1 cell transcription factor, can upregulate genes encoding IFN-γ and CXCR3 involved in sarcoidosis." (PMID 39904950, 2025). "The bronchoalveolar lavage cell levels of TBX21 mRNA in patients with sarcoidosis are higher than those in controls." (PMID 39904950, 2025). "In sarcoidosis, the expressions of IFNγ and Tbx21 in CD4+ T-cells are up-regulated post-T-cell activation." (PMID 26254778, 2015).
major depressive disorder (4 papers, 2013 to 2025). An episode of depression lasting two or more weeks without an intervening episode of mania. "TBX21 (T-bet) which drives the Th1 immune response, is linked to the major depressive disorder (MDD) phenotype." (PMID 37950255, 2023). "The TBX21 rs41515744, rs17244587 and rs2325717 polymorphisms have been linked to the major depressive disorder (MDD) phenotype." (PMID 37950255, 2023). "The team of Wong ML, in 2008, discovered the correlation between depression and two SNPs of rs17244587 in TBX21 and rs2296840 in PSMB4 genes in the American-Mexican population." (PMID 37950255, 2023). "According to this study, polymorphisms in many inflammatory-related genes including TBX21, NR3C1 are associated with the risk of major depression and antidepressant response." (PMID 37950255, 2023). "TBX21 has been shown to be involved in major depressive disorder (MDD) and the antidepressant response." (PMID 37950255, 2023).
parasitemia (4 papers, 2019 to 2021). "However, our group and others have recently observed that Tbx21-/- mice maintained IFN-γ producing CD4+ T cells during parasite infection, while remaining highly susceptible to infection." (PMID 33465134, 2021). "Despite the absence of follicles, a rapid accumulation of Aicda+ GC-like B cells followed first parasitemia peak clearance, accompanied by the occurrence of Xbp1+ expressing CD138+ plasma B cells and Tbx21+ atypical CD11c+ memory B cells." (PMID 34762705, 2021).
Peripheral T-cell lymphomas (4 papers, 2020 to 2024). "In peripheral T-cell lymphoma, not otherwise specified, (PTCL, NOS) two molecular subtypes have been identified with the help of gene expression profiling studies: PTCL-GATA3 and PTCL-TBX21, characterized by overexpression of the transcription factors TBX21 or GATA3." (PMID 38835969, 2024).
psoriasis (4 papers, 2018 to 2025). An autoimmune condition characterized by red, well-delineated plaques with silvery scales that are usually on the extensor surfaces and scalp. "Regarding the initiation phase of psoriasis, the expression of the transcription factor Tbx21 associated with Th1 cells was significantly downregulated at 3 days after exposure, while this was no longer detectable at the later time point (2 weeks)." (PMID 41341581, 2025).
rheumatoid arthritis (4 papers, 2016 to 2023). A chronic, systemic autoimmune disorder characterized by inflammation in the synovial membranes and articular surfaces. "For example, transcriptome analysis of CD21-/lo versus CD21+ mature naïve B cells from subjects with rheumatoid arthritis or common variable immunodeficiency found that TBX21 expression was upregulated in CD21-/lo B cells." (PMID 28953967, 2017).
systemic sclerosis (4 papers, 2015 to 2023). A chronic disorder, possibly autoimmune, marked by excessive production of collagen which results in hardening and thickening of body tissues. "T-bet, encoded by the TBX21 gene, was involved in systemic sclerosis and Crohn’s disease." (PMID 26370572, 2015). "TBX21 rs11650354 was also a susceptibility factor in systemic sclerosis." (PMID 26370572, 2015). "TBX21 SNPs may correlate with some neurodegenerative diseases, such as systemic sclerosis." (PMID 37950255, 2023).
type 1 diabetes (4 papers, 2007 to 2023). "We genotyped one TBX21 SNP (His33Gln; rs2240017), which had previously been associated with type 1 diabetes in a Japanese case and control collection." (PMID 18045485, 2007). "We did not obtain any evidence of an association between type 1 diabetes and either ICAM1, IL12B or TBX21, all of which had previously been associated with type 1 diabetes." (PMID 18045485, 2007).
Alzheimer disease (3 papers, 2023 to 2025). A progressive, neurodegenerative disease characterized by loss of function and death of nerve cells in several areas of the brain leading to loss of cognitive function such as memory and language. "This study investigated the association between the TBX21 immune gene and the possibility of late-onset Alzheimer’s disease (LOAD) incidence in 194 LOAD and 200 control subjects using the real-time qPCR and the Tetra-ARMS-PCR methods." (PMID 37950255, 2023). "In this study, we show that the TBX21 immunity gene has an overall > 2-fold elevated mRNA expression level in the leucocytes of peripheral blood in patients with late-onset Alzheimer’s disease (LOAD)." (PMID 37950255, 2023). "Our results show for the first time the likely impact of the TBX21 (T-bet) immune gene in LOAD development and that the elevated TBX21 mRNAs in the WBCs of LOAD patients may represent a new easy diagnostic test for Alzheimer’s disease." (PMID 37950255, 2023).